MTOR (mechanistic target of rapamycin kinase)
Diseases named in the same sentence as MTOR in open-access papers (continued):
Sharing a sentence is not in itself a finding about the gene and the disease.
cancer (continued). "The importance of mTOR signaling for stromal cell activation has been described in cancer-associated fibroblasts, dermal fibroblasts, and hepatic stellate cells." (PMID 34651016, 2021). "Downstream of the activation of VEGFR2, several signaling pathways are activated, including PI3K/AKT/mTOR signaling, the activation of which is one of the hallmark signaling pathways in cancer and angiogenesis." (PMID 34066403, 2021). "PTEN loss results in the downstream activation of AKT/mTOR signaling in secondary cancer lesions and determines the survival of the overall ccRCC patients." (PMID 34563045, 2021). "The AKT/mTOR signaling pathway has been implicated in the progression of various cancers via phenomena such as drug resistance, autophagy, and the Warburg effect." (PMID 33968986, 2021). "We also suggest that the strong anti-cancer properties of Evr in GEMres cells are closely linked to mTOR-mediated glucose metabolism and the Warburg effect." (PMID 33849427, 2021). "Mounting evidence shows that dysregulation of the AMPK/mTOR signalling pathway is associated with a variety of cancers." (PMID 33752745, 2021). "Higher mTOR activity scores are associated with a worse prognosis in several tumor types (metastasis, leading to metastasis-related cancer mortality)." (PMID 35029792, 2021). "Somatic mutations in the PI3K-Akt-mTOR pathway are often found in cancer tumorigenesis and can be used as a target for treatment of cancer patients." (PMID 34217313, 2021). "The gene encoding the components of the PI3K-AKT-mTOR signaling axis is often mutated in cancer, but mTOR, which encodes mTOR kinase, is rarely mutated." (PMID 34533198, 2021). "In summary, our data demonstrate that the optimized biguanide derivatives in this study can indeed inhibit cancer cell growth associated with the AMPK/mTOR signaling pathway with a more effective activity than that of proguanil." (PMID 34641319, 2021). "For example, inhibition of plasma membrane localized GRP78 causes inactivation of the PI3K/AKT/mTOR pathway in cancer cells." (PMID 34252884, 2021). "The wide-ranging regulatory roles of mTOR in metabolic homeostasis have established this protein complex as a central controller of various physiological functions, and dysregulation of mTOR has been linked to disease states including cancer." (PMID 34062764, 2021). "The mTOR pathway is often dysregulated in cancer and recently, activating mutations of mTOR were identified in several human cancers making mTOR a potential therapeutic target for cancer treatment." (PMID 35054445, 2021). "Dysregulation of the mTOR pathway is frequently associated with a variety of human diseases, such as cancers, metabolic diseases, and cardiovascular and neurodegenerative disorders." (PMID 33670113, 2021). "Stimulation of AMPK and the inhibition of mTOR is another pathway employed to activate autophagy when cancer cells undergo amino acid and glucose deficiency." (PMID 33802014, 2021). "The PI3K/AKT/mTOR signaling pathway was implicated in a wide spectrum of cancers, neurological diseases, and proliferative disorders." (PMID 34938313, 2021). "The phosphatidylinositol 3-kinase (PI3K)/v-Akt murine thymoma viral oncogene (AKT)/mTOR pathway is activated across many cancer lineages, and it is associated with cancer development and metastasis." (PMID 34670536, 2021). "More recently, BCAA defects have also been implicated in autism, cancer, obesity, diabetes and heart failure by modulating nutrient sensing pathways such as mTOR and insulin, as well as ROS and glutamine homeostasis." (PMID 34091011, 2021). "A previous study showed that PI3k/AKT/mTOR signaling is an important mechanism associated with increasing radiation sensitivity in various cancer types." (PMID 33471836, 2021). "Hyperactivation of the PI3K/AKT/mTOR pathway is associated with drug resistance and cancer progression." (PMID 33790792, 2021).
cancer (continued). "Overactivation of mTOR is commonly reported in cancer and is extensively associated with poor prognosis." (PMID 33918290, 2021). "As alpelisib and everolimus specifically target the PI3K/Akt/mTOR pathway, we performed targeted next-generation sequencing to test for mutations in 64 cancer genes, including the PI3K pathway genes." (PMID 33498451, 2021). "Intriguingly, the results of GSEA of TCGA datasets showed that the cancer-promoting effect of PYCR2 was closely associated with the PI3K/AKT/mTOR pathway in CRC." (PMID 34512817, 2021). "To further identify the functional annotation, GSEA was employed, and we found the more abundant autophagy-related pathways and processes in the high-risk group, such as the MTOR signaling pathway and autophagy in cancer." (PMID 34414116, 2021). "mTOR has a central role in regulating many fundamental cell processes, and its deregulation has been implicated in the progression of human cancers, including HCC." (PMID 34638365, 2021). "Elements of the AKT/PI3K/mTOR signaling pathway can be mutated or dysregulated in cancer, causing hyper-activation of the pathway and affecting chemosensitivity, apoptosis, proliferation, and other biological processes." (PMID 34095461, 2021). "The AKT/AMPK/mTOR signalling is the major regulatory pathways associated with cellular autophagy, apoptosis, cell proliferation, migration, and angiogenesis in cancer." (PMID 34174900, 2021). "Knockdown of mTOR in LAL deficient MDSCs suppressed their stimulation on proliferation of several cancer lineages, including B16 melanoma, Lewis lung carcinoma and transgenic mouse prostate cancer-C2 cancer cells." (PMID 34281263, 2021). "An aberration in the PI3K/Akt/mTOR signaling pathway has been linked to cancer development, neuroinflammation, and dysregulation of microglia function." (PMID 34439380, 2021). "Autophagy also makes mTOR-mutated cancer cells tolerant to mTOR inhibitors by eliminating receptor-interacting protein kinases (RIPKs), which promote necroptosis when autophagy is inhibited." (PMID 34835393, 2021). "Over a decade ago, it was proven that the combination of trastuzumab with everolimus can rescue cancer cells from trastuzumab resistance caused by alterations in the PI3K/AKT/mTOR signalling pathway, with greater efficacy than either agent alone." (PMID 34204960, 2021). "In fact, activation of the PI3K/Akt/mTOR pathway is one of the major causes of current cancer chemotherapy resistance." (PMID 34221232, 2021). "Deregulated mTOR is associated with many pathophysiological conditions such as aging, Alzheimer’s disease, diabetes, obesity, and cancer." (PMID 34361836, 2021). "This is consistent with previous studies that have observed MTORC1 activation from NDD- and cancer-associated MTOR variants." (PMID 34197453, 2021). "Although mTOR kinase itself is rarely mutated in cancer, it is easily hijacked by upstream oncogenic nodes, including those in the PI3K/Akt pathway and the MAPK pathway driven by Ras." (PMID 34863080, 2021). "DDIT4 is induced by cellular stress conditions and regulates mTOR activity 7, and its abnormal expression has been linked to multiple diseases, including malignant tumors 16-17." (PMID 34659532, 2021). "This panel of genes considered upregulation of known cancer-related pathways (e.g., mTOR signaling) to distinguish high- from low-risk cancer cases." (PMID 33785068, 2021). "The AKT/mTOR signaling pathway is known to be an important mediator of cancer progression, and its activation is associated with unfavorable outcomes." (PMID 34943938, 2021). "We demonstrate that pathogenic MTOR variants, in both NDDs and in cancer, likely activate proteins by indirectly increasing exposure to the catalytic site." (PMID 34197453, 2021). "Aberrant activation of the PI3K/AKT/mTOR pathway, a major pathway that regulates proliferation, apoptosis, and cell cycle progression, is implicated in the development of several cancers." (PMID 33668685, 2021).
cancer (continued). "A great number of mutations found in HCC involve abnormal upregulation of mTOR expression, and tumors with increased signaling of mTOR have been recently identified as a subset of aggressive cancers." (PMID 34638365, 2021). "Preclinical studies have suggested that the PI3K/AKT/mTOR signaling pathway influences stemness, a dedifferentiation-related cellular phenotype associated with aggressive cancer." (PMID 34762647, 2021). "The protein kinase B or AKT is one of the most critical intracellular pathways associated with mTOR signaling, and it has been considered as the master regulator for most of the cancers." (PMID 34017854, 2021). "The growth factor–mediated PI3K/Akt/mTOR axis is a frequently activated pathway in cancer cells due to AKT1 mutation, loss of PTEN, or PI3K activator mutation." (PMID 34658867, 2021). "Taken together, the feedback activation of the STAT3 signaling pathway in PTEN-deficient cancer cells limits the therapeutic efficiency of PI3K/mTOR inhibitors, which can be circumvented by targeting the PI3K and STAT3 pathways simultaneously." (PMID 33431808, 2021). "The PI3K/AKT signaling cascade is frequently upregulated in human cancers, causing hyperactivation of the Mammalian target of rapamycin (mTOR) pathway." (PMID 33479203, 2021). "GSEA results showed that many cancer-related signaling pathways such as PI3K/Akt/mTOR pathway and TGF-β/SMAD pathway were enriched in high-risk group." (PMID 33712026, 2021). "This is a viable pan-cancer treatment strategy since it overcomes the limited efficacy of mTOR inhibitors as well as the drug-resistance associated with activation of mTOR." (PMID 33935721, 2021). "The activated PI3K/Akt/mTOR pathway has been implicated in various autoimmune diseases and it is a common finding in cancer, including hematologic malignancies." (PMID 34948236, 2021). "Overexpression of CCNB1 was associated with various cancer types, and predicted inferior response to mTOR inhibitor." (PMID 34051812, 2021). "Signaling via mTOR is linked to accelerated aging and dysregulation of mTOR signaling is also linked to the progression of cancer, inflammatory and neurological diseases, as well as T2DM." (PMID 34421827, 2021). "Although molecular mechanisms for the link between DM and OvCa are yet to be uncovered, there are theories to explain this relationship, including the IGF-I/PI3K/AKT/mTOR pathway used to explain pathogenic connections between DM and other cancers." (PMID 34440224, 2021). "This is mainly because it had a higher translational potential than the other molecules and because mTOR signaling is considered a hallmark of cancer, with various clinical trials on pharmacological mTOR inhibitors." (PMID 34575669, 2021). "Abnormal activation of the PI3K/Akt/mTOR pathway has been associated with the development of several types of cancers, including GBM." (PMID 34063168, 2021). "Hyperactive mTOR signaling is a major cause of human diseases such as cancer, and the selective mTOR inhibitor rapamycin is an effective chemotherapy agent." (PMID 33897695, 2021). "The suppression of the Akt/mTOR signals caused by artocarpin resulted in the inhibition of cancer cell transition to mesenchymal phenotypes." (PMID 33920031, 2021). "Targeting the pathway component mTOR in cancer associated fibroblasts was demonstrated to reduce chemoresistance in PDAC." (PMID 34805167, 2021). "Dysregulation of the AMPK/mTOR pathway has been widely reported in various cancers, and AMPK inactivation is also closely associated with aggressive malignant behaviors and serves as a promising therapeutic target." (PMID 34772914, 2021). "Loss of function mutations of phosphatase and tensin homolog (PTEN), a negative regulator of PIK3/AKT/MTOR, increase PIK3/AKT/MTOR pathway activation and are associated with cancer development." (PMID 34440837, 2021).
cancer (continued). "Essentially, the PI3K/AKT/mTOR pathway is likely one of the most frequently mutated pathways in human cancers; it is closely related to autophagy and therefore represents a potential point of attack." (PMID 34207792, 2021). "The mTOR pathway is reported to be aberrantly active in several cancers, including PDAC, in part due to mutations in upstream regulatory molecules including PTEN, AKT, and TSC1/2." (PMID 34638443, 2021). "In cancer cell lines activation of the protein kinase B (Akt)/mammalian target of rapamycin (mTOR) signalling pathway causes proteasomal-mediated degradation of NPC1." (PMID 34183444, 2021). "In fact, activation of the mTOR/RPS6 pathway has been associated with cancer cell survival, inflammation, and neoangiogenesis through various upstream regulators." (PMID 35008473, 2021). "Cancer associated-survival pathways such as PI3K/Akt/mTOR pathway are able to stimulate HK2 in cancer cells, inducing drug resistance." (PMID 34885243, 2021). "Murine ccRCC models and human ccRCC cancers feature mTOR activation and cellular overgrowth after loss of VHL and PBRM1 gene function." (PMID 33920158, 2021). "As a result, the identified targets genes were mainly enriched in cancer-related pathways, such as hallmark UV response, Wnt signaling pathway, and mTOR signaling pathway." (PMID 33510968, 2021). "In this setting, metformin blocks both the mTOR signaling pathway and the senescence-associated reprogramming of cancer stemness induced by CDK4/6 inhibitor, a known Jekyll and Hyde of CDK4/6 inhibition in cancer treatment." (PMID 33494247, 2021). "The mechanistic target of rapamycin (mTOR) regulates several biological mechanisms implicated in tumor progression, including cancer cell proliferation and tumor angiogenesis." (PMID 33802831, 2021). "Aberrant PI3K/AKT signaling, which is a major cause of hyperactivation of the mTOR pathway, has been reported in many human cancers, and is contributing to both cancer pathogenesis as well as therapy resistance." (PMID 34044827, 2021). "Based on accumulating evidence, the PI3K/AKT/mTOR signaling pathway is abnormally activated in many cancers, causing apoptosis deregulation and chemotherapeutic resistance." (PMID 34279440, 2021). "DDIT4 also known as REDD1 or RTP801, is expressed in response to diverse stress conditions and its abnormal expression is linked to cancer via the effects on PI3K/Akt/mTOR signaling." (PMID 34107956, 2021). "Given its importance in a great variety of cellular processes, it is not surprising that mTOR dysregulation is implicated in diseases such as cancer, and that synthetic inhibition of mTOR is being exploited as a therapeutic option." (PMID 34209164, 2021). "The majority of the cancer-associated mutations occur in the mechanistic/mammalian target of rapamycin (mTOR) gene." (PMID 35582305, 2021). "The high levels of HER2 also cause elevated activation of mechanistic target of rapamycin (mTOR) and enhanced glucose metabolism, both of which support cancer growth." (PMID 34208071, 2021). "PI3K/Akt/mTOR is another classical pathway that has been found to be associated with many types of cancer." (PMID 34944829, 2021). "Taken together, simultaneous targeting of STAT3 and the PI3K/mTOR pathway can sensitize PTEN-deficient cancer cells to BEZ235, and inhibit tumor growth in vivo." (PMID 33431808, 2021). "The PI3K/AKT/mTOR pathway has previously been associated with the regulation of pathways involving glucose uptake and glycolysis in cancer." (PMID 34968247, 2021). "The PI3K/AKT/mTOR signaling pathway is constitutively active in PTEN-deficient cancer cells, and its targeted inhibition has significant anti-tumor effects." (PMID 33431808, 2021). "Several studies showed that mTOR inhibitors have an increased antitumoral activity in cancer patients with loss of PTEN." (PMID 32100259, 2020).
cancer (continued). "Several signaling transduction pathways of cancer have been implicated in autophagy, such as the Akt/mTOR pathway and the Beclin 1/Bax pathway, and recent studies have reported that ROS are important triggers of autophagy under various circumstances." (PMID 33321911, 2020). "The PI3K/AKT/mTOR pathway is currently a widely studied intracellular signaling pathway and is directly associated with cellular quiescence, proliferation, cancer and longevity." (PMID 31904088, 2020). "Emerging studies have shown that mTOR-associated pathways are closely related to cell growth and metabolism in different human disorders, including cancers." (PMID 33343350, 2020). "The PI3K/AKT/mTOR pathway is activated in many kinds of cancers and mainly mediated by mutations in the p110α subunit of PI3K called PIK3CA (>80%)." (PMID 32899250, 2020). "The PI3K/AKT/mTOR signaling cascade is among one of the most frequently deregulated mechanisms in cancer, often as a result of genetic alterations and/or mutations." (PMID 32340135, 2020). "mTOR dysregulation is implicated in the tumorigenesis of many cancers, however, this is unclear for EC." (PMID 32679719, 2020). "The PI3K/AKT/mTOR pathway is one of the most frequently dysregulated pathways in cancer, up to 30% of human cancers have obtained mutations in one or several members of this pathway." (PMID 33045011, 2020). "A candidate gene approach focused on the AKT/mTOR pathway should allow to discover low penetrance alleles that would increase susceptibility to cancer or reduce the age of the onset disease." (PMID 33247671, 2020). "FBXW7 promotes mTOR ubiquitination/degradation in cancer cells and gliocytes, while FBXW7 deficiency increases the sensitivity of a variety of human tumors to rapamycin." (PMID 33291075, 2020). "In this view, PTEN acts as a tumor suppressor, preventing PI3K/Akt/mTOR activation, and is highly mutated in a variety of human cancers, including breast cancer, melanoma, and lung and prostate carcinoma." (PMID 31952362, 2020). "Emerging evidence suggests that the mammalian target of rapamcyin (mTOR) pathway is associated with radio-resistance in cancer treatment." (PMID 31959810, 2020). "SIRT1, AKT1, and MTOR oscillate in both cell lines in a circadian manner and are associated with the circadian clock and cancer hallmarks." (PMID 32295075, 2020). "The phosphoinositide 3 kinase/mammalian target of rapamycin (PI3K/mTOR) signalling pathway is involved in quiescence and cell survival and is linked to cancer, where its over-activation has an anti-apoptotic effect." (PMID 32987769, 2020). "The mTOR pathway has been implicated in the emergence of resistance to BRAFi in various cancer types including CMM31,32." (PMID 33082316, 2020). "Correspondingly, the knockdown of these mutants in cancer cells cause augmented autophagy by affecting signaling at various phases of the autophagic process with a concomitant stimulation of mTOR signaling." (PMID 33614491, 2020). "Biologically, T2D and cancers are associated with an abnormality in the PI3K–AKT signaling pathway (mainly at mTOR level), mostly upregulated in neoplastic tissue and downregulated in insulin target tissues in case of T2D." (PMID 33552973, 2020). "Hyperactivating and recurrent mutations in mTOR that have been associated with cancer appear to cluster to the FAT and KD, and some have been shown to increase the catalytic activity of mTORC1 and/or reduce the threshold for Rheb-induced activation in vitro." (PMID 32759652, 2020). "In two HSIL samples, we detected the p.H1047R mutation of PIK3CA, which was shown to be associated with the response to PI3K/AKT/mTOR signaling pathway inhibitors administered to patients with diverse advanced cancers." (PMID 32664330, 2020). "Akt/mTOR is an important signaling pathway for cell survival, which is closely associated with cancer progression and development." (PMID 33071789, 2020).